CDCA8 (cell division cycle associated 8)
Diseases named in the same sentence as CDCA8 in open-access papers (continued):
Sharing a sentence is not in itself a finding about the gene and the disease.
cancer (59 papers, 2012 to 2025). A tumor composed of atypical neoplastic, often pleomorphic cells that invade other tissues. "In analogy with its role in cancer, the overexpression of CDCA8 WT caused a higher cell proliferation rate compared to the control (GFP), whereas the sumoylation mutant lost this ability." (PMID 39940913, 2025). "For instance, CDCA8 has been associated with promoting cancer progression by binding with NF-YA and has been considered a potential therapeutic target for HCC patients." (PMID 38627714, 2024). "Cell division cycle‐associated 8 (CDCA8) is involved in numerous signaling networks, and it serves a crucial modulatory function in multiple malignant tumors." (PMID 36855818, 2023). "CDCA8 is a strong modulator of mitosis and cell division, and it is intricately linked to cancer development and progression." (PMID 36855818, 2023). "In fact, all CDCAs, particularly, CDCA2, CDCA3, CDCA5, and CDCA8, exhibit direct associations with cell cycle and proliferation among almost all cancers." (PMID 36855818, 2023). "In analyzing the association of human cancers with immune cells and chemokines, we found that CDCA8 expression was positively correlated with human immune cells Act-CD4 (rho = 0.465, p < 0.01), Th2, MeM-B and chemokines CCL in PCa." (PMID 35449575, 2022). "After Cox regression analysis by collating OS, PFI, and DSS data of human cancers associated with CDCA8, human cancer was expressed using a deep forest plot." (PMID 35449575, 2022). "CDCA8 is a critical regulator of mitosis and cell division and is associated with cancer growth and progression." (PMID 31410192, 2019). "Cell division cycle associated 8 (CDCA8) is an important multifactorial regulator in cancers." (PMID 36639822, 2023). "Therefore, we infer that KNTC1 can bind and interact with CDCA8, causing an increase in unstable mitotic spindles, eventually leading to the occurrence and development of cancer by regulating the cell cycle." (PMID 35852618, 2023). "In addition, the study has verified NF-Y as a positive regulator of CDCA8 transcription, which unearthed the underlying activation of CDCA8 expression in embryonic stem cells and cancer cells." (PMID 35517403, 2022). "At the same time, loss of CDCA8 inhibited the growth of cancer cells and induced apoptosis." (PMID 35449575, 2022). "Significant association was observed between high expression of CDCA8 and shorter cancer-specific survival (P < .0001, HR = 0.2752, 95% CI: 0.1364-0.5554), so was the case in the high expression of CDCA8 and shorter overall survival (P < .0001, HR = 0.4270, 95% CI: 0.2630–0.6930)." (PMID 30142792, 2018). "Specifically, CDCA2 and CDCA8 play significant roles in cell division and chromosome segregation, and mutations in these genes may lead to chromosomal instability, a characteristic feature of many cancers, including GBM." (PMID 40114265, 2025). "Thus, the aberrant expression of CDCA8 is strongly associated with cancer pathogenesis." (PMID 33685433, 2021). "Subsequently, the expressions of CDCA2, CDCA3, CDCA4, CDCA5, CDCA7, and CDCA8 genes in COAD samples across various cancer stages were verified using the GEPIA2 database." (PMID 39924497, 2025). "It is reported that nuclear transcription factor Y (NF-Y) can transcriptionally activate the expression of CDCA8 in cancer cell." (PMID 36639822, 2023). "Actually, CDCA8 is transcriptionally activated in human embryonic stem cells (hESCs) and cancer cells, but slightly, or even absently, expressed in normal tissues." (PMID 36991473, 2023). "In conclusion, we assessed CDCA8 expressions in pan‐cancer, and compared its profile among HCC and para‐cancerous tissues." (PMID 36855818, 2023). "Accumulating evidence suggests that CDCA8 dysregulation is observed in many cancers and is essential for cell survival and metastasis for gastric, kidney, colorectal, lung, and breast cancers." (PMID 36639822, 2023).
cancer (continued). "The results showed that the protein expressions of BUB1 (P < 0.001), BUB1B (P = 0.025), CCNA2 (P < 0.001), and CDCA8 (P = 0.002) were significantly up-regulated in the cancer tissues." (PMID 37853361, 2023). "As for potential upstream targets of CDCA8, previous literature had suggested that the CDCA8 was transcriptional promoted by NF-Y in cancer cells." (PMID 36639822, 2023). "Similar to previous studies, we found that the CDCA8 levels was highly increased in the multiple cancer types, including HCC." (PMID 36639822, 2023). "Previous studies demonstrated that overexpression of CDCA8 was responsible for cancer growth and progression." (PMID 36991473, 2023). "The expression of LPCAT1, NDRG1, G6PD, CYP7A1, SPP1, SFN, and CDCA8 was significantly higher in cancer tissues than in paraneoplastic tissues, whereas the expression of DNASE1L3 was significantly lower in cancer tissues." (PMID 37717019, 2023). "CDCA8 levels were elevated in cancer tissues compared to adjacent normal tissues (p < 0.0001, n = 71)." (PMID 36639822, 2023). "We used the TISIDB online database to analyze the link between CDCA8 expression and immune cell infiltration in cancers." (PMID 35449575, 2022). "Further analysis found the correlation between CDCA8 expression and cancer stage (P = 0.037), and CDCA8 higher expression was observed in patients with advanced stage." (PMID 35517403, 2022). "Studies have confirmed that CDCA8 plays a crucial role in mitosis, chromosome segregation, and cancer cell division." (PMID 35449575, 2022). "A preliminary mechanism study was performed by detecting the effects of CDCA8 silencing on the expression of apoptosis related proteins or classical cancer related molecules." (PMID 35517403, 2022). "In 15 pairs of PCa and prostate normal tissues from the TCGA database, CDCA8 expression was significantly higher in cancer than in normal controls." (PMID 35449575, 2022). "Another interesting phenomenon is that higher CDCA8 gene expression is positively correlated with the poor prognosis of which cancers." (PMID 35449575, 2022). "The expression of CCND1 and CDK4/6, which are well-acknowledged regulator not only in cell cycle but also in cancer progression, was also found to be downregulated upon CDCA8 knockdown 37-39." (PMID 35517403, 2022). "Investigating the differential expression of CDCA8 between human tumors and normal tissues, the expression levels of CDCA8 in pan-cancer were analyzed using the TCGA database." (PMID 35449575, 2022). "CDCA8 involves the regulation of mitosis and has been described as a potential prognostic biomarker in several cancers." (PMID 36699449, 2022). "All the investigations highlighted the clinical value and significance of CDCA8 in cancer progression." (PMID 35517403, 2022). "By retrieving related literature, we found that CDCA5 and CDCA8, as important regulatory proteins in the cell cycle in cancer, were recognized as oncogenes." (PMID 33449451, 2021). "CDCA8 is an integral part of the chromosomal passenger complex, which is involved in mitosis and contributes to distant metastasis of cancer cells." (PMID 33778011, 2021). "CDCA8 expression was significantly lower in normal tissues than in cancer tissues (P = 1.794 × 10−19)." (PMID 33685433, 2021). "Then, several enriched signaling pathways such as HIPPO and interferon signaling pathways and disease and functions such as cancer were distinguished to construct the CDCA8-related interaction network." (PMID 33542211, 2021). "Previous studies have reported that upregulated CDCA8 expression plays an important role in malignant transformation, cancer growth and progression." (PMID 33685433, 2021). "Accumulating evidence showed the upregulation of CDCA8 in human cancers and highlighted its biological functions in tumorigenesis." (PMID 33542211, 2021).
cancer (continued). "In conclusion, two multiple cancer-associated genes including CDC20 and CDCA8 were identified as candidate diagnostic biomarkers for BC by analyzing GEO, Oncomine, GTEx, THPA and TCGA data." (PMID 32677673, 2020). "Among them, seven genes of CDCAs (CDCA1/NUF2: P = 2.73E-22, CDCA2: P = 1.52E-16, CDCA3: p = 1.50E-20, CDCA5: P = 1.77E-20, CDCA6/CBX2: P = 6.87E-19, CDCA7: P = 5.92E-16, and CDCA8: P = 1.67E-18) were all up-regulated in 19 cancer datasets." (PMID 33665158, 2020). "Higher expression of CDCA8 predicted poor cancer-specific survival (P < .0001, HR = 0.2752, 95% CI:0.1364-0.5554) and overall survival (P < .0001, HR = 0.4270, 95% CI: 0.2630–0.6930) in patients with BC." (PMID 30142792, 2018). "The CCLE analysis for the CDCA8 expression in different cancer cell lines showed a high expression in breast and other types of cancers." (PMID 29467944, 2018). "Previous studies demonstrated that overexpression of CDCA8 was required for cancer growth and progression." (PMID 30142792, 2018). "Plk1, Aurka, Aurkb and Cdca8 are in the top 50 co-expressed genes, these play an important role in cancer formation." (PMID 23039964, 2012). "The AURKB/CDCA8 pathway is potentially pivotal in cancer pathogenesis." (PMID 39787178, 2025). "CDCA8, a crucial regulator of mitosis, is upregulated in numerous cancer types." (PMID 38742112, 2024). "Our findings revealed that the expression of CDCA8 alone or in combined with NF-YA contributed to cancer progression, and could serve as novel potential therapeutic targets for HCC patients." (PMID 36639822, 2023). "Through the ROCK signaling pathway, CDCA8 knockdown may inhibit cancer cell proliferation and invasion." (PMID 35449575, 2022). "CDCA8 plays an important role in several types of cancer, and its overexpression may act as an oncogene." (PMID 35627287, 2022). "CDCA8 was confirmed to play a role in promoting malignant tumor progression." (PMID 35449575, 2022). "In particular, CDCA8 is necessary for the kinetochore attachment-error correction and for the stability of the bipolar spindle in human mitosis and, in disease states, it can contribute to distant metastasis of cancer cells." (PMID 35884419, 2022). "Through the ROCK signalling pathway, CDCA8 knockdown might inhibit cancer cell proliferation and invasion." (PMID 34741389, 2021). "Four proteins (KRT14, Hornerin [HRNR], Cell Division Cycle Associated 8 [CDCA8], and Fibronectin Type III Domain Containing 3B [FNDC3B]) were identified as unique to all patient HGSC cells at the cancer–mesothelial interface following this high-stringency approach." (PMID 31443478, 2019). "The copy number of CDCA8 was also high in breast and other cancers." (PMID 29467944, 2018). "Additionally, the absence of significant differences in the mRNA expression levels of CDCA2, CDCA3, CDCA4, CDCA5, CDCA7, and CDCA8 across different cancer stages of COAD suggests that these genes may play a consistent role throughout the progression of COAD." (PMID 39924497, 2025). "Besides, CDCA8, as the key mediator of estrogen-stimulated cell proliferation in cancer cells, could inhibit cancer cell survival and growth by cell cycle G1 phase arrest." (PMID 33665158, 2020). "One report revealed that aurora kinase B (AURKB) phosphorylates CDCA8 in vitro, and a simultaneous co‐transactivation of CDCA8 and AURKB is typically seen in multiple cancers." (PMID 36855818, 2023). "Therefore, we hypothesize that CDCA8 may be a cancer-promoting biomarker for PCa." (PMID 35449575, 2022). "The results showed that CDCA8 was highly expressed in ACC, BLCA, BRCA, ESCA, PRAD, and UCS cancer compared with each normal tissue." (PMID 35449575, 2022). "In the present study, VEGFA, RRM2, H2AFX, CHEK1, CEP55, CDCA8 and AURKA were significantly upregulated; however, VCL, TPM2 and TPM1 were significantly downregulated in cancer samples of BC." (PMID 34112125, 2021).
cancer (continued). "The genes CDC20, CDCA8, and CEP55 were prognostic in more than three (multiple) cancer types while other genes were specific for particular cancer types, such as MYEOV for PAAD." (PMID 32489468, 2020). "CDCA8, a part of the chromosomal passenger complex (CPC), plays an important role in the cell division cycle in cancer cells." (PMID 32677673, 2020). "Studies have reported that the transcriptional activity of CDCA8 was increased in embryos, embryonic stem cells, and cancer cells, and its expression was very weak or not expressed in normal tissues." (PMID 37059592, 2023). "CDCA8, AURKB and PLK1 were also three hub ICPs in multiple kinds of cancers." (PMID 37770497, 2023). "CDCA8 was considered to be a hypothetical oncogene, upregulated in many types of cancer tissues, but very low or absent in normal tissues, which was consistent with our findings." (PMID 35168617, 2022). "Previous studies have reported the increased transcriptional activity of CDCA8 in embryos, embryonic stem cells and cancer cells however, CDCA8 is not expressed or is very weakly expressed in normal tissues." (PMID 33685433, 2021). "Multivariate COX regression analysis results showed that CDCA8 expression was independent of other clinical factors only in cancer-specific survival." (PMID 32377458, 2020). "Interestingly, the genes CDC20, CDCA8, MYBL2, C1QTNF6, CEP55, CDK1 and KIF14 were found to be more universal/common, since they mark multiple types of cancers not only in prognosis but also in diagnosis." (PMID 32489468, 2020). "In agreement with RT-PCR data (above), HRNR, KRT14, and CDCA8 were detected in cancer cell lysates but not in the mesothelial cell controls." (PMID 31443478, 2019). "The mean expression levels of CDCA8 in cancer tissues were significantly higher than those in relevant normal tissues (P = .0039)." (PMID 30142792, 2018). "We found seven upregulated genes (MCM10, RAD51-associated protein 1 (RAD51AP1), KIF2C, Y_RNA, FAM64A, CDC6, and CDCA8) and six downregulated genes (ADAMTS8, ATP1A2, MYH1, OGN, OMD, and ZBTB16) in at least two phenotypes containing either ALT high/middle or TEL high/middle regardless the cancer type." (PMID 38763334, 2024). "We analyzed RNA sequencing expression data of 9736 tumors and 8587 normal samples from The Cancer Genome Atlas (TCGA) and the Genotype-Tissue Expression (GTEx) projects for the expression profiles of centrosome clustering proteins KIFC1, AURKB, BIRC5, and CDCA8." (PMID 39335162, 2024). "Here, several growth-associated genes were up-regulated, including RNA helicase (HELLS), PRR11, CDCA8, and DNA topoisomerase 2 (TOP2A), HMGB2, EIF2B4, and CDKN3, which are thought to serve important functions during growth stimulation, many of which are known to be up-regulated in various cancers." (PMID 37907238, 2024). "Indeed, of the eight CRC GWAS loci found within this subset of CRC-related smoking genes, CDCA8, CDKN3, FADS1, FADS2, MYBL2, PCSK9, and PRC1, have all been reported to be overexpressed in others cancers and to play important roles in the DNA damage response pathway." (PMID 37509213, 2023). "In vitro, CDCA8, Survivin and INCENP were required for activation and/or localization of Aurora B. Our study and the previous studies suggested that Borealin could affect the growth and progression of cancer cells." (PMID 30142792, 2018).
infection (3 papers, 2017 to 2023). The state of being infected such as from the introduction of a foreign agent such as serum, vaccine, antigenic substance or organism. "We designed three distinct CDCA8 lentiviral silent infection sequences, and utilized qRT‐PCR to demonstrate the effective silencing of the CDCA8 gene with CDCA8‐sh1 and CDCA8‐sh2 (p < 0.001)." (PMID 36855818, 2023). "The derived fluorescence in >80% of cells proved the successful infection, and the significantly downregulated level of CDCA8 in SHG-44 and U251 cells." (PMID 33542211, 2021).
adenocarcinoma (1 paper, 2024). A common cancer characterized by the presence of malignant glandular cells. "The present results also exhibit that among the amplified genes, the following eight genes involved in the cell cycle were found to be amplified in more than 5% of HGSO adenocarcinoma patients: ATAD2, ASF1B, CCNE1, CDC20, CDCA8, RECQL4, RNASEH2A, and SMC4." (PMID 39199556, 2024).
CDCA8 also shares sentences with these, for which no sentence is quoted: colorectal cancer (7 papers); cholangiocarcinoma (2); glioblastoma (2); liver diseases (2); adrenocortical carcinoma (1); brain glioma (1); cervical cancer (1); Cirrhosis (1); colon cancer (1); Hepatitis (1); invasive breast carcinoma (1); invasive ductal breast carcinoma (1); invasive lobular breast carcinoma (1); liver fibrosis (1); male breast carcinoma (1); neuroblastoma (1); oesophageal cancer (1); papillary thyroid carcinoma (1); preeclampsia (1); Primary hypothyroidism (1); psoriasis (1); thyroid (1); thyroid hypoplasia (1); thyroid nodule (1); thyroid tumor (1); uterine fibroids (1).